INS (insulin)
Diseases named in the same sentence as INS in open-access papers (continued):
Sharing a sentence is not in itself a finding about the gene and the disease.
diabetes (continued). "More than 97% of Iranian adults with a diagnosis of diabetes consume oral glucose-lowering agents, inject insulin or use a combination of medications and insulin." (PMID 29044139, 2017). "Here we present an update of this publication, including the most recent CVOTs on GLP-1 RAs, SGLT-2 inhibitors, Insulin degludec and acarbose and discuss their implications for the medication of type 2 diabetes mellitus (T2DM) patients." (PMID 29020969, 2017). "Controlling hyperglycemia in diabetes has been found to be difficult, as it requires high doses of oral antidiabetic agents and insulin." (PMID 28642704, 2017). "Of the patients with uncontrolled diabetes, 49% (n = 29) were on two oral agents and only 10% (n = 6) were on insulin." (PMID 28245810, 2017). "We also report the influence of oxidative stress protein DCN-2 on the systemic production of NO and insulin in different diabetes individuals." (PMID 28811499, 2017). "“Each participant received overall orientation on diabetes management (including how to inject insulin) as well as nutritional and exercise education”." (PMID 29025693, 2017). "As expected, we saw strong associations between insulin, GIP, and PP and self-reported diabetes after correction for multiple comparisons." (PMID 28753646, 2017). "Diabetes mellitus can be managed by diet, physical exercise, and modern drugs (insulin and/or oral hypoglycemic drugs such as sulfonylureas and biguanides)." (PMID 28464813, 2017). "Already more than 25 years ago it was shown that oral administration of insulin was effective in delaying the onset and decreasing the incidence of diabetes in NOD mice." (PMID 29387056, 2017). "After insulin administration, memory and verbal fluency improved, and perfusion was elevated in the insula cortex of participants with diabetes, suggesting the involvement of an insulin mechanism." (PMID 28424581, 2017). "The Arabic translation of the DNT-15 was found to have good numerical reasoning testing properties among insulin using patients with diabetes." (PMID 28472140, 2017). "This classified them between the healthy subjects (MCR: 8.5 ± 0.5 ml·kg−1·min−1) and the insulin-resistant individuals with type 2 diabetes mellitus (3.2 ± 0.8 ml·kg−1·min−1)." (PMID 29234684, 2017). "Transplantation of insulin-producing cells (IPCs) was once thought to be the most promising strategy for treating diabetes, but the pace from the laboratory to clinical application has been obstructed due to its drawbacks." (PMID 28515792, 2017). "Insulin resistance is a major characteristic of obesity and type 2 diabetes mellitus, and ER stress appears to directly inhibit insulin signaling pathways." (PMID 28650993, 2017). "Of note, in the metformin (n = 20) and in the insulin + metformin (n = 10) groups, six and two subjects respectively were also on other oral diabetes medication (Sitagliptin or Glimepiride)." (PMID 28947922, 2017). "Severe hypoglycemia is a frequently encountered medical emergency, seen commonly in patients with diabetes who are taking drugs such as insulin or insulin secretagogues (e.g., sulfonylurea)." (PMID 28148284, 2017). "In diabetes, blood sugar levels increase because of insufficient insulin in the body or because body cells cannot efficiently unitize insulin." (PMID 28387741, 2017). "In the diabetes group at baseline, insulin pump use, total cholesterol, HDL cholesterol and HbA1c were significant, R2 = 0.151 for the model." (PMID 28683835, 2017). "The association between PHF and type 2 diabetes (T2DM) is unclear and some studies point to insulin treatment, hypoglycaemic episodes consequently to inadequate control of diabetes or, more recently, to an alteration of trabecular bone." (PMID 29228945, 2017). "Aggressive control of blood glucose concentration using insulin is one approach, but it is unlikely that insulin alone can substantially improve cardiovascular outcomes in patients with diabetes." (PMID 28690837, 2017).
diabetes (continued). "In early stage type I diabetes trials, for example, polyelectrolyte-modified islet cells have been studied as a route to restore healthy production of insulin—a molecule dysregulated during diabetes." (PMID 30970718, 2017). "Although diabetes was controlled equally whatever the route of insulin administration, liver 11β-HSD1 gene expression and activity was decreased only in the IP group, suggesting that a first hepatic pass is needed for 11β-HSD1 hepatic inhibition." (PMID 28458655, 2017). "Induction of diabetes decreased the level of insulin, leptin and high density lipoprotein (HDL) and increased the level of other lipids, glucose, and hepatic enzymes significantly (p<0.05)." (PMID 28348972, 2017). "Any intervention in the IGT phase that reduces resistance to insulin or protects the β-cells, or both, should prevent or delay progression to diabetes." (PMID 28045450, 2017). "Only 5% of the hyperglycaemic patients received insulin and these were the same women who had diabetes in pregnancy." (PMID 28464913, 2017). "Type 1 diabetes mellitus (T1DM) results from an autoimmune attack against the insulin-producing ß cells which leads to chronic hyperglycemia." (PMID 28729721, 2017). "Diabetes mellitus (DM) is a metabolic disease characterized by hyperglycemia resulting from defects in insulin secretion, insulin action, or both." (PMID 28348533, 2017). "Changes in serum insulin level in diabetes reflect abnormalities in β-cell function or insulin action." (PMID 28431540, 2017). "GOD-mediated microdevices with accurate insulin-loading capacity are a potential candidate for diabetes therapy." (PMID 30970930, 2017). "The course of diabetes mellitus type 2 is highly dependent on the preservation of a healthy beta-cell mass and insulin secretion capacity, which both are notably impaired by oxidative stress and disturbed redox signaling." (PMID 28542222, 2017). "Recent advances in the differentiation of pluripotent stem cells (PSCs) into functionally glucose-responsive insulin-producing β-like cells have pushed the promise of cell therapy for diabetes closer to reality." (PMID 28813430, 2017). "Diabetes treatment varies according to the presentation and insulin is frequently necessary for glycemic control." (PMID 28101143, 2017). "iPSCs were reprogrammed from fibroblasts from patients with HNF1A diabetes and differentiated into insulin-positive cells." (PMID 28951826, 2017). "Empowered by the constant increase of diabetes cases among the population and the degenerative nature of the disease, the insulin market has grown at a 7% annual rate during the past decade." (PMID 28829407, 2017). "Mothers with higher educational levels can deal better with diabetes and its treatment requirements, which include physical activity, proper diet, and insulin dosage." (PMID 28218068, 2017). "Diabetes mellitus, one of the most common chronic diseases, results from reduced insulin secretion or insulin response in the peripheral tissues." (PMID 28859155, 2017). "One of them is diabetes relapse in patients with growing weight due to insulin-stimulated fat accumulation." (PMID 28884000, 2017). "Type 2 diabetes mellitus patients were on the following diabetic medications: oral hypoglycemic drugs (83.1%), oral hypoglycemic drugs and insulin (13.5%), and dietary management (3.5%)." (PMID 27994108, 2017). "Diabetes mellitus (DM) is a chronic metabolic disorder characterized by hormonal dysregulation in insulin-producing pancreatic β-cells." (PMID 29117231, 2017). "Because of the patient’s hyperglycemia without acidosis, we presumptively diagnosed that he had newly developed diabetes mellitus and considered the possibility of insulin depletion as a result of repeated acute pancreatitis." (PMID 28610599, 2017). "Deletion of insulin specifically in thymic Aire expressing mTECs enhanced diabetes development in both male and female mice." (PMID 29312143, 2017).
diabetes (continued). "Pyruvate kinase, one of the major enzymes involved in glucose homeostasis, shows remarkable crosstalk with insulin levels in individuals with diabetes." (PMID 28662169, 2017). "All of the patients who had poor results had insulin-dependent diabetes mellitus and had been using insulin for an average of 9.5 years (distribution 8-12)." (PMID 29375258, 2017). "Since 1899 vanadium had been used for diabetes treatment as the only compound available for this purpose until the discovery of insulin." (PMID 28072841, 2017). "A total of 121 women received a diagnosis after age 30, which is considered to be most likely type 2 diabetes, and in this group, age of onset of diabetes was 51.3 years for those taking insulin." (PMID 27832382, 2017). "Although, oral hypoglycemic agents and insulin are the mainstays of treatment of diabetes and are effective in controlling hyperglycaemia, they have prominent side effects and fail to significantly alter the course of diabetic complications." (PMID 28064559, 2017). "Diabetes mellitus is a group of physiological dysfunctions characterized by hyperglycemia resulting directly from inadequate insulin secretion, insulin resistance, or excessive glucagon secretion." (PMID 28587101, 2017). "Diabetes Mellitus (DM) is a metabolic disease characterized by hyperglycemia due to defects in insulin secretion by pancreatic β-cells, insulin action on target tissues or a combination of both." (PMID 28282933, 2017). "The results of this experiment demonstrate that the addition of acarbose or metformin to patients with Type-1 diabetes mellitus who are controlled with insulin is commonly well tolerated and help to improve metabolic control in patients." (PMID 28811795, 2017). "Main Outcome Measures: During a follow-up of up to 14.7 years (between April 1, 1997, and Jan 1, 2012) 139 cases of pre-diabetes, 110 cases of T2D and 26 cases of insulin initiation were identified." (PMID 28258520, 2017). "Studies in rodent models have shown that elevated CMPF values impair glucose-stimulated insulin secretion, increase advanced glycation end products and oxidative stress, and impair insulin granule maturation to accelerate diabetes development." (PMID 28596534, 2017). "We find our human data of specific interest since one of the signatures of T2D is reduced first‐phase insulin secretion prior to full‐blown diabetes." (PMID 29122960, 2017). "In 2009, Kim and colleagues studies showed that mice present human-type islets when subjected to pathologic conditions characterized by an increased demand for insulin, such as inflammation, obesity, diabetes, and pregnancy." (PMID 28798911, 2017). "Studies have indicated that other inflammatory cytokines such as IL-1β and IFN-γ which are increased in obesity and diabetes also modulate insulin signaling." (PMID 28251163, 2017). "T2DM or noninsulin-dependent diabetes mellitus is the most common form of diabetes in which the body has adequate insulin, but the cells have become resistant to it, accounting for 90%–95% of the diabetic cases." (PMID 28798859, 2017). "Type 2 diabetes mellitus (T2DM) is a group of metabolic diseases characterized by hyperglycemia resulting from resistance to insulin action and an inadequate compensatory insulin secretory response." (PMID 28431542, 2017). "Iron has a role in diabetes development by three mechanisms: decreased insulin production, increased resistance to insulin, and hepatic dysfunction of glucose metabolism even in the absence of excess iron." (PMID 28580448, 2017). "Self-monitoring of blood glucose is essential in patients with diabetes who are on intense insulin regimen (three to four injections of basal and prandial or insulin pump)." (PMID 28167928, 2017). "Type 2 diabetes mellitus is a complex disease characterised by insufficient secretion of insulin from pancreatic beta cells (beta cell failure) in the setting of insulin resistance." (PMID 28770320, 2017).
diabetes (continued). "A retrospective analysis of discharge summaries of all patients who were being treated with insulin and were included in the 2016 National Inpatient Diabetes Audit was conducted." (PMID 28852529, 2017). "Besides being a methodological bedrock for experiments aiming to elucidate the role of insulin signalling in the brain, the question is whether nasal insulin administration therefore represents an attractive alternative medical regimen to current therapies to treat obesity-associated diabetes." (PMID 28469281, 2017). "Successful diabetes management involves managing medical responsibilities (including blood glucose monitoring and insulin administration) alongside behaviors around diet and physical activity." (PMID 30291057, 2017). "At present, however, app users and HPs must remain cautious with diabetes apps, especially those in the insulin dose calculator category." (PMID 28666975, 2017). "This condition is different from insulin resistance in diabetes for which Akt activation by insulin is impaired due to other mechanisms." (PMID 29118381, 2017). "The data presented shows the relationship between pre-existing use of injectable insulin in women diagnosed with breast cancer and type 2 diabetes mellitus, the growth factor profiles at the time of breast cancer diagnosis, and subsequent cancer outcomes." (PMID 28239632, 2017). "Increased type 2 diabetes risk in HFE hemochromatosis is associated with one or more factors, including iron overload, decreased insulin secretion, increased BMI, IR, MetS, diabetes in first-degree relatives, and cirrhosis." (PMID 28331855, 2017). "Early onset diabetes participants had higher fasting insulin than participants with diabetes onset between 44–61 years and lower 2-hour postprandial insulin (IN2h) values than late-onset diabetes participants." (PMID 28422176, 2017). "Diabetes mellitus is a metabolic disorder, characterized by hyperglycemia that develops as a consequence of defects in insulin secretion." (PMID 30965879, 2017). "First, differences in glucose and insulin levels at follow-up visits were evaluated after excluding patients who had already been incidentally diagnosed with diabetes outside the study." (PMID 28759599, 2017). "The effect of diabetes on the cancer progress can be also interpreted using insulin and insulin-like growth factor 1(IGF-1) signaling pathways." (PMID 28977962, 2017). "This study analyzes the frequency and predictors of hypoglycemia in insulin-treated diabetes in an ambulatory setting." (PMID 28913365, 2017). "As a main LPS receptor, CD14 sets the tone of insulin sensitivity and thus determines the occurrence of metabolic diseases including obesity and diabetes." (PMID 29064399, 2017). "Exogenous insulin aids in glucose control, but is inherently different than endogenous insulin, which prevents the microvascular and macrovascular complications of diabetes." (PMID 28831150, 2017). "Therapeutic approaches are needed to delay the progression of β-cell destruction and replace lost insulin production in patients with type 1 diabetes mellitus." (PMID 29073149, 2017). "Diabetes mellitus (DM) is a chronic disease which is characterized by an impaired production or utilization of insulin, leading to high amounts of blood glucose." (PMID 28133716, 2017). "Pramlintide, with a mechanism of action that complementary to the insulin, offers such an alternative and is the only anti-diabetes therapy other than insulin which is approved for use in patients with T1DM." (PMID 29029531, 2017). "Type 2 diabetes mellitus (T2DM) is a global disease characterized by abnormal metabolism of blood glucose, lipid and protein caused by insulin resistance or abnormal insulin secretion." (PMID 29029615, 2017). "This indicates that the deterioration of insulin signaling in pancreatic α-cells in diabetes can play certain roles in the dysregulation of glucagon secretion similar to that in the classical target organs for insulin activity." (PMID 28426798, 2017).
diabetes (continued). "A recent study investigated the contribution of children’s experiences about diabetes self-care during the early stages of development of a video game about insulin injections." (PMID 30291061, 2017). "These had predictable half-lives in circulation when used to treat diabetics, before dissociating to insulin monomers that bound the insulin receptors and mediated the uptake of glucose." (PMID 28875019, 2017). "According to many previous studies, patients with diabetes mellitus have been shown to have defects in sensitivity of target organs and tissues to insulin and to relatively inadequate insulin output." (PMID 28386567, 2017). "Diabetes mellitus is a group of metabolic diseases characterized by elevated blood glucose concentration (hyperglycaemia) resulting from either defects in insulin secretion by the pancreas, insulin action or both." (PMID 28877765, 2017). "It is worth to note, that vitamin D was proposed to be a factor influencing insulin sensitivity and its supplementation was recommended, to prevent diabetes." (PMID 28316011, 2017). "Baseline data included age, sex, ethnicity, marital status, educational level, employment status, health-related quality of life (WHOQOL-BREF), insulin use, diabetes-related complications and HbA1c." (PMID 29089913, 2017). "The three groups that developed diabetes showed a gradual increase in average fasting insulin concentrations over a 10-year period." (PMID 28266592, 2017). "Recent evidence suggests that alterations in cardiac metabolism that occur in diabetes mellitus contribute towards this contractile dysfunction, particularly due to the insulin resistance detected in the diabetic heart in numerous studies." (PMID 28933367, 2017). "Knowing the answer would facilitate not only the optimization of the differentiation protocols but also the selection of cells with high insulin production to maximize the ratio of secreted hormone over the number of cells needed for diabetes correction." (PMID 28680477, 2017). "Type 2 diabetes mellitus is a chronic and slowly evolving disease characterised by impaired insulin-mediated glucose uptake in peripheral tissues and a failure of the insulin secreting capacity of the pancreas." (PMID 28612106, 2017). "In conclusion, this real-world study demonstrated the diversity of recent SGLT2i usages with mainly prescribed in long-standing diabetes as a ‘last resort’ therapy before insulin treatment." (PMID 29213337, 2017). "The glucose-recognition insulin release profiles endowed the nanogel with promising application in self-regulated insulin delivery systems for the treatment of diabetes." (PMID 28772528, 2017). "For our diabetes team, adjusting insulin levels and ketosis monitoring during intercurrent diseases, as well as reinforcement of diabetes acceptance behavior will be the main points of our educational program from now on." (PMID 28702090, 2017). "These glucose level-dependent mechanisms of incretins suggest that DPP-4 inhibitors can improve glycemic control and reduce glucose fluctuations in patients with type 2 diabetes mellitus compared with other insulin secretagogues." (PMID 28725273, 2017). "We aimed to assess the safety and efficiency of the novel sodium glucose co-transporter 2 (SGLT2) inhibitor in combinations with insulin for type 1 and type 2 diabetes mellitus (T1DM and T2DM)." (PMID 28538386, 2017). "Being a key factor in all types of diabetes, we determined insulin levels in serum obtained at the end of the observation period." (PMID 28281693, 2017). "The use of apps to record blood glucose was the most favored function in apps used by people with diabetes, with interest in insulin dose calculating function." (PMID 28666975, 2017). "In type 2 diabetes mellitus (T2DM), the failure of pancreatic β-cells results from chronic exposure to a high level of circulating glucose, which causes insufficient insulin secretion or loss of insulin action at target tissues." (PMID 28788070, 2017).